RNU6-708P (RNA, U6 small nuclear 708, pseudogene)
Gene: Small nuclear RNA gene on chromosome 18 (48,169,784 to 48,169,890, reverse strand). Ensembl gene ENSG00000206944.
Homologues: Orthologues: chimpanzee U6 (95% identical), macaque U6 (93% identical), mouse Gm24423 (89% identical), mouse Gm22716 (86% identical), rat LOC120097299 (85% identical), rat LOC120099391 (84% identical), mouse Gm23142 (83% identical), mouse Gm26240 (83% identical), mouse Gm23926 (73% identical), rat LOC120097194 (69% identical). Paralogues in human: RNU6-1060P (92% identical), RNU6-116P (92% identical), RNU6-1124P (91% identical), RNU6-12P (91% identical), RNU6-13P (91% identical), RNU6-32P (91% identical), RNU6-33P (91% identical), RNU6-41P (91% identical), RNU6-42P (91% identical), RNU6-1 (90% identical), RNU6-15P (90% identical), RNU6-17P (90% identical), and 1285 more.